JAZF1 (JAZF zinc finger 1)
Diseases named in the same sentence as JAZF1 in open-access papers (continued):
Sharing a sentence is not in itself a finding about the gene and the disease.
asthma (4 papers, 2020 to 2026). "Variants in JAZF1 with genome-wide significant associations with asthma, T2D and at least one anthropometric measure." (PMID 37377600, 2023). "To further explore the two genome-wide significant variants identified in the JAZF1 region shared between asthma, T2D and height, we conducted mediation analyses in the discovery dataset with T2D as the outcome, mediated by either asthma or height." (PMID 37377600, 2023). "We were able to identify cross-phenotype associations for three of our phenotypes of interest (asthma, T2D, and height), identifying variants in JAZF1 that were significantly associated with all three phenotypes." (PMID 37377600, 2023). "Additionally, this study is the first attempt at dissecting whether there are overlapping causal variants and/or biological pathways for these phenotypes and provides the strongest evidence for an association of variants in and around JAZF1 with asthma." (PMID 37377600, 2023). "Additionally, the identified childhood-onset asthma-associated gene of JAZF1 has evidence of genetic interactions with identified genes of AHI1, NSMCE1, TDRKH, CD52, and HLA-DRB1 based on a genome-wide map of genetic interaction inferred from radiation hybrid genotypes." (PMID 32867763, 2020). "We link discovered eQTLs to associations identified in pediatric and adult asthma and atopy traits, nominating 78 eGenes like TRAF3, ZBTB10 and JAZF1 in disease relevant cell types." (PMID 41889912, 2026). "Fine-mapping of the JAZF1 region, suggests independent credible sets for each phenotype, with asthma and T2D each having one independent credible set and height having four credible sets which do not overlap with those for asthma or T2D." (PMID 37377600, 2023). "Fine-mapping analyses suggested that within JAZF1 there are non-overlapping regions harboring causal susceptibility variants for asthma, T2D, and height." (PMID 37377600, 2023). "Univariate fine-mapping results in the JAZF1 region for asthma, T2D and height." (PMID 37377600, 2023). "For example, strong evidence is found for site-specific DNAm as an intermediary via which disease variants regulate ORMDL3, GSDMB, and JAZF1 expression by CD4+ T cells in RA, MS, and asthma, and a similar mechanism in relation to ANKRD55 and IL6ST is limited to RA and MS." (PMID 31945409, 2020). "Fine-mapping of the JAZF1 region identified one credible set for asthma, a second, non-overlapping credible set for T2D and four non-overlapping credible sets for height." (PMID 37377600, 2023). "These functional studies suggest the plausibility of the role of JAZF1 in asthma and T2D, but do not suggest a genetic link between these phenotypes." (PMID 37377600, 2023).
Hepatic steatosis (3 papers, 2018 to 2025). Steatosis is a term used to denote lipid accumulation within hepatocytes. "In the current study, we first generated JAZF1-Tg mice and then investigated the role of JAZF1 in age-associated and nutrient-induced hepatic steatosis." (PMID 30154417, 2018). "Taken together, data from both in vivo and in vitro experiments clearly indicated that JAZF1 signaling was a potential process in hepatic steatosis occurring during aging and nutrient excess." (PMID 30154417, 2018). "The inhibitory effects of hepatic steatosis in JAZF1-Tg mice, however, were disappeared during aging." (PMID 30154417, 2018). "Data suggested a possible involvement of JAZF1 in both genetic- and environmental-related hepatic steatosis in animals and humans." (PMID 30154417, 2018). "Nevertheless, as a pilot study, data from our experiments are of interest to reveal the potential link between JAZF1 and hepatic steatosis." (PMID 30154417, 2018). "Data from our experiments may provide the first evidence to understand the molecular mechanisms of JAZF1 in aging and nutrient-induced hepatic steatosis with sterol regulatory element-binding protein 1c (SREBP-1c)-dependent pattern." (PMID 30154417, 2018). "To investigate whether JAZF1 is involved in hepatic steatosis, we examined hepatic JAZF1 expression in db/db mice, C57BL/6 J fed with HFD and adiponectin knockout (Adipoq KO) mice, and patients with NAFLD." (PMID 30154417, 2018).
sarcoma (3 papers, 2019 to 2025). A usually aggressive malignant neoplasm of the soft tissue or bone. "In addition, low-grade endometrial stroma sarcoma harbors specific chromosomal rearrangements involving JAZF1 and PHF1." (PMID 31309284, 2020). "This category refers to high-grade sarcomas that contain a low-grade component, which may or may not be associated with JAZF1 fusions, and often show signs of dedifferentiation." (PMID 40507372, 2025).
uterine tumors (3 papers, 2018 to 2022). "It is currently unknown why these fusions are associated with uterine tumors, let alone with new pathogenic subgroups of ESS, but it is intriguing that two of these known JAZF1 fusions (with PHF1 or SUZ12) could directly alter PRC2 function." (PMID 35328741, 2022).
endometriosis (2 papers, 2017 to 2023). The growth of functional endometrial tissue in anatomic sites outside the uterine body. "Of note, a low methylation level of JAZF1 has been correlated with a stronger effect of decitabine in endometriosis." (PMID 36765607, 2023).
papillary carcinoma of the thyroid (2 papers, 2020 to 2024). "JAZF1 expression in papillary thyroid cancer tissues is negatively associated with a high incidence of disease progression, recurrence of the tumor (p=0.031), unfavourable disease-free survival rate and unfavourable overall survival rate (p=0.030)." (PMID 32856873, 2020). "We found a positive association between TFAP2B and AP-1 expression in papillary thyroid carcinoma patients, but due to a few studies which assessed their expression, we assessed the expression of another biomarker which is JAZF1." (PMID 32856873, 2020). "In conclusion, we demonstrated that expression levels of TFAP2B and AP-1 protein were increased while the expression levels of JAZF1 were decreased in papillary thyroid carcinoma in comparison with non-neoplastic thyroid tissues using immunohistochemistry." (PMID 32856873, 2020).
systemic lupus erythematosus (2 papers, 2017 to 2023). An autoimmune multi-organ disease typically associated with vasculopathy and autoantibody production. "We made an intersection of the up-DPpGCs in Pla-KO1l3 with the genes for ‘systemic lupus erythematosus’ in the GWAS catalog and found three genes in common, namely, JAZF1, DOCK10, and BACH2." (PMID 38255187, 2023). "We found JAZF1 to be the only gene common with the GWAS term ‘systemic lupus erythematosus and systemic sclerosis’." (PMID 38255187, 2023).
uterine sarcoma (2 papers, 2020 to 2025). "LGESS is the second most common uterine sarcoma after LMS and is reportedly characterized by specific gene rearrangements such as JAZF1::SUZ12, JAZF1::PHF1, and EPC1::PHF1." (PMID 40072062, 2025).
adenosarcoma (1 paper, 2023). A low grade malignant neoplasm characterized by the presence of a benign epithelial component (tubular and cleft-like glands) and a low grade sarcomatous component that contains varying amounts of fibrous and smooth muscle tissues. "The JAZF1-BCORL1 rearrangement is predominantly associated with uterine stromal sarcomas; thus far, ours is the second report of the same in an adenosarcoma." (PMID 36639698, 2023). "Since BCOR was shown to be strongly expressed in adenosarcoma carrying the JAZF1-BCORL1 fusion gene, we examined the expression of BCOR in our case by immnohistochemistry using an anti-BCOR monoclonal antibody (clone C-10, Santa Cruz Biotechnology, Dallas, TX)." (PMID 36639698, 2023).
arteriolosclerosis (1 paper, 2015). The thickening of the wall of the small arteries and arterioles. "Results from another study show that JAZF1 variants are also associated with arteriolosclerosis." (PMID 26500707, 2015).
Arthritis (1 paper, 2020). Inflammation of a joint. "We validated cis-meQTL effects at 3 loci implicated by CIT (cg21124310/ANKRD55, cg07522171/JAZF1, and cg17134153/FCRL3) in an independent cohort of 39 patients with early arthritis using pyrosequencing." (PMID 31945409, 2020).
breast carcinoma (1 paper, 2015). "The AIM eliciting the strongest association with breast cancer was rs10486576 on 7p15 within locus JAZF1 (per allele OR = 2.0; 95% CI 1.2, 3.1; p = 0.01)." (PMID 25783644, 2015).
cardiac tumors (1 paper, 2018). "The common JAGs responsible for heart diseases included: JARID2 and TBX20, associated with a structural heart anomaly; JAZF1, associated with cardiac tumors; CAMK2G, associated with conduction defects; and CMAK2D and TMPO, associated with dilated cardiomyopathy." (PMID 29449671, 2018).
diabetic nephropathy (1 paper, 2015). "Certain variants in the JAZF1 locus are associated abnormal pancreatic β-cell function, which plays a role in the pathogenesis of T2DM and are significantly associated with impaired glucose regulation as well as diabetic nephropathy." (PMID 26500707, 2015).
esophagitis (1 paper, 2025). An acute or chronic inflammatory disease affecting the esophageal wall. "The second patient carrying the JAZF1 variant was a 61-year-old man with subacute SSc, diffuse cutaneous form, with cutaneous, vascular, and pulmonary involvement and esophagitis." (PMID 41283471, 2025). "The association was also found with skin lesions, Raynaud’s phenomenon, ILD, and esophagitis (χ2 = 16.2–40.9, p < 0.0001), though further studies with larger cohorts are required to determine whether JAZF1 contributes synergistically to pro-fibrotic and vascular mechanisms in SSc." (PMID 41283471, 2025).
hyperlipidemia (1 paper, 2021). "Therefore, it is speculated that JAZF1 may play an important role in diabetic macroangiopathy, hyperlipidemia and glycolipid metabolism." (PMID 33722242, 2021).
lymph node metastasis (1 paper, 2019). "Meanwhile, we validated in 120 GC patients specimens that low miR-1275expression and high JAZF1 mRNA expression levels were closely associated with lymph node metastasis and poor prognosis." (PMID 31357957, 2019). "In contrast, JAZF1 expression was increased in GC tissues and was positively associated with lymph node metastasis (P = 0.008) and Borrmann type (P = 0.032)." (PMID 31357957, 2019).
osteoporosis (1 paper, 2023). A condition of reduced bone mass, with decreased cortical thickness and a decrease in the number and size of the trabeculae of cancellous bone (but normal chemical composition), resulting in increased fracture incidence. "Next, we analysed six selected SNPs in 631 patients evaluated for osteoporosis [rs2707518 (CPED1/WNT16), rs3779381 (WNT16), rs115242848 (LOC101927709/EN1), rs10239787 (JAZF1), rs603424 (PKD2L1) and rs6968704 (JAZF1)]." (PMID 37831088, 2023). "Six of these SNPs, mapping to WNT16, EN1, JAZF1, and PKD2L1, were genotyped among 631 patients evaluated for osteoporosis." (PMID 37831088, 2023). "From this list, we selected the five SNPs with the lowest p-values for further analyses in patients evaluated for osteoporosis: rs2707518 (CPED1/WNT16), rs3779381 (WNT16, intron 1), rs115242848 (LOC101927709/EN1), rs10239787 (JAZF1, intron 2), and rs603424 (PKD2L1, intron 2)." (PMID 37831088, 2023).
ovarian tumors (1 paper, 2020). "A break-apart FISH assay for BCOR, PHF1, and JAZF1 was negative in all components of the ovarian tumors." (PMID 32290854, 2020).
Pca (1 paper, 2022). "The results showed that the higher expression levels of JAZF1, PRDM6, RBMS3, and TSHR were correlated with the poor prognosis of Pca patients." (PMID 35959113, 2022). "In the regulatory networks of target genes of the sDMIRs, we found that JAZF1, PRDM6, RBMS3, and TSHR were correlated with the poor prognosis of PCa patients." (PMID 35959113, 2022).
Pleural effusion (1 paper, 2025). The presence of an excessive amount of fluid in the pleural cavity. "Analysis of DEGs in Cycling GZMA and GZMA CD4 T cells from pleural effusion of HP and LCP revealed that seven transcription factors (MLLT3, KLF12, FOXP1, NFKB1, ZEB2, TOX, JAZF1) were upregulated in both cycling GZMA CD4 and GZMA CD4 cells in MPE of LCP." (PMID 40959273, 2025).
prediabetes (1 paper, 2020). "In conclusion, our present results show that mild prediabetes induces miRNA expression changes leading to altered gene expression of Jazf1, Zkscan1, and Rap2c, which may contribute to the diastolic dysfunction and may serve as potential drug targets." (PMID 32244869, 2020).
prostate tumor (1 paper, 2024). "Module 3 includes NTRK2, DDR2, and STAT5B, which have been associated with prostate tumor metastasis, and JAZF1, ZEB1, and BCL2, which have been linked to cancer progression and resistance to chemotherapy." (PMID 39347576, 2024).
sickle cell disease (1 paper, 2022). Sickle cell anemias are chronic hemolytic diseases that may induce three types of acute accidents: severe anemia, severe bacterial infections, and ischemic vasoocclusive accidents (VOA) caused by sickle-shaped red blood cells obstructing small blood vessels and capillaries. "Recently, a genome-wide association study of an African American cohort with sickle cell disease reported a single nucleotide polymorphism (SNP) of ZNF802/JAZF1 (SNP ID = rs740127, base position 28,004,900) associated with high HbF levels with a low genome-wide significance." (PMID 35322124, 2022).
steatosis (1 paper, 2018). Increased lipid within the cytoplasm of cells. "In accordance with the decreased liver TG content, hematoxylin and eosin (H&E)-stained liver slides revealed less steatosis in SD-fed JAZF1-Tg mice compare to the WT littermates on the same diet during aging." (PMID 30154417, 2018). "Both ALT and AST levels were also lower with aging in JAZF1-Tg mice compare with age-matched WT mice, consistent with attenuated liver injury and steatosis." (PMID 30154417, 2018). "In JAZF1-Tg mice, body fat content and hepatosteatosis were protected from HFD-induced steatosis, and accompanied by decreased lipogenesis gene expression." (PMID 30154417, 2018).
uterine adenosarcoma (1 paper, 2023). "Both spindle cells in the corpus uteri and the intra-abdominal mass showed partial nuclear positivity for BCOR, suggesting that the intra-abdominal mass was a metastatic tumor derived from the preceding uterine adenosarcoma that may carry the JAZF1-BCORL1 fusion gene." (PMID 36639698, 2023).
cancer (20 papers, 2010 to 2025). A tumor composed of atypical neoplastic, often pleomorphic cells that invade other tissues. "The expression of JAZF1 was dramatically suppressed in cancer cells transfected with miR-200b mimics, whereas the levels of JAZF1 were significantly increased in the presence of miR-200b inhibitors." (PMID 39834817, 2024). "In this study we also found a new YWHAE-JAZF1 cancer fusion transcript that most probably results in enhanced activity of JAZF1 moiety." (PMID 34527573, 2021). "For example, JAZF1 prefers the 3′ full-length promoter (prmtr.40310) in KIRP cancer, whereas in KIRC cancer, a truncated promoter (prmtr.40312) is favored." (PMID 33727936, 2021). "Collectively, our study demonstrated a novel molecular link between low miR-1275 expression and cancer metastasis in GC tumorigenesis by downregulating vimentin and upregulating E-cadherin upregulation via JAZF1 targeting." (PMID 31357957, 2019). "For example, the region in chromosome 7 (gene JAZF1) is active in healthy tissues, hence producing the transcriptional repressor, while in cancer tissues it is heterochromatized and, consequently, the repressor is not being transcribed." (PMID 30486775, 2018). "But the exact role of JAZF1 in cancer is still uncertain needing further studies." (PMID 32856873, 2020). "In addition, colony formation ability, one of cancer’s main characteristics, was enhanced in Jazf1-overexpressing cell lines." (PMID 29416651, 2018). "Nevertheless, since deregulation of JAZF1 expression has been strongly correlated with type 2 diabetes (T2D) and oncogenesis in many studies, it is probable that the transcriptional regulatory function of this zinc finger protein is of particular importance in islet or cancer cells." (PMID 33445503, 2021). "Recently, we provided evidence that expression of a designer chimeric RNA targeting JAZF1 and SUZ12 genes in human endometrial stromal cells also drives the formation of JAZF1-SUZ12, a cancer fusion gene commonly found in low-grade endometrial stromal sarcomas patients." (PMID 35326453, 2022). "We did not identify any correlations of total gene expression with cancer status for the JAZF1, MSMB, HNF1B, MYEOV or CTBP2 genes." (PMID 20569440, 2010). "However, RNAseq analysis detected a previously unknown in-frame cancer fusion transcript of genes YWHAE and JAZF1, directly supported by nine sequencing reads." (PMID 34527573, 2021). "Indeed, 50% of ESSs do not harbor a JAZF1 and YWHAE rearrangement by FISH, which represents an insufficient examination for the characterization of these cancers." (PMID 32933053, 2020).
tumor (17 papers, 2010 to 2024). "JAZF1 expression is negatively associated with huge tumor size (0.023), vascular invasion (p=0.007) and unfavorable overall survival rate (p=.030)." (PMID 32856873, 2020). "Based on the evidence of loss of expression for normal versions of JAZF1 in multiple tumors suggests a possible role of this gene as a tumor suppressor." (PMID 20368795, 2010). "The JAZF1 gene is located at 7p15, and it encodes for a zinc finger protein that is overexpressed in the human prostate tissue where it induces cell proliferation, migration, and invasion, and tumor development." (PMID 35625981, 2022). "JAZF1 may encode a tumor suppressor since loss of expression is associated with neoplastic development in multiple tumor types involving these translocations, though the mechanism of protective activity is unknown." (PMID 24497837, 2014). "The tumor promoter JAZF zinc finger 1 (JAZF1) is a repressor of TGF-β-activated kinase 1 (TAK1), which is involved in NF-kB signaling cascade." (PMID 36834660, 2023). "Further study indicated that miR-200b negatively regulated the expression of the tumor promoter JAZF zinc finger 1 (JAZF1)." (PMID 36387211, 2022). "Tumor formation capacity was enhanced in Jazf1-overexpressing cells and decreased in Jazf1 knock-down cells compared to control DU145 cells." (PMID 29416651, 2018). "Tumor-specific mRNA transcript for predicted protein contains 5-prime end of the JAZF1 and 3-prime end of the SUZ12 sequence, with retaining zinc finger motifs from both genes." (PMID 26879382, 2016). "Therefore, JAZF1 could promote GC tumour metastasis by promoting vimentin expression and suppressing E-cadherin expression via direct transcriptional repression." (PMID 31357957, 2019). "Additionally, a growing body of evidence is showing that the loss of expression for normal version of the JAZF1 in various malignancies, thus suggesting that the JAZF1 may have a role as a tumor suppressor gene." (PMID 26879382, 2016). "Subsequent studies of larger tumor series using RT-PCR and fluorescence in situ hybridization (FISH) have shown the occurrence of the JAZF1/SUZ12 fusion gene not only in ESS but also in endometrial stromal nodules and, less frequently, in undifferentiated endometrial sarcomas." (PMID 22761769, 2012). "The second tumor harboring a MDM2 amplification had high‐grade morphology, polysomy of JAZF1, PHF1, and YWHAE but no rearrangements were reported, leading to a diagnosis of UUS." (PMID 32352245, 2020). "Although the specific functions of JAZF1 and the PHF1 and their role in ESS-pathogenesis are not clear, one can expect that based on their zinc finger motifs they are involved in regulation of transcriptional processes in tumor cells." (PMID 26879382, 2016).